TTC36 (tetratricopeptide repeat domain 36)
Synonyms: HBP21
Tractability: No criterion of Open Targets' tractability assessment is met for any kind of drug.
Gene: Protein-coding gene on chromosome 11 (118,527,437 to 118,531,197, forward strand). Ensembl gene ENSG00000172425.
Subcellular location (Human Protein Atlas): Nucleoplasm
Gene Ontology:
Molecular function: protein sequestering activity
Biological process: negative regulation of peptidyl-threonine phosphorylation; negative regulation of proteasomal ubiquitin-dependent protein catabolic process; negative regulation of protein polyubiquitination; negative regulation of SCF-dependent proteasomal ubiquitin-dependent catabolic process
Cellular component: cytosol
Genetic constraint (gnomAD): Loss-of-function variants: 16 observed, 12.95 expected, observed/expected ratio (o/e) 1.24, 90% interval 0.83 to 1.8. The upper end of that interval is the gene's LOEUF score, 1.8, which puts it in group 6 of 6, group 1 being the genes least tolerant of losing a copy. Missense variants: 288 observed, 211.64 expected, observed/expected ratio (o/e) 1.36, 90% interval 1.24 to 1.5. Synonymous variants: 111 observed, 87.08 expected, observed/expected ratio (o/e) 1.27, 90% interval 1.09 to 1.49.
Homologues: Orthologues: macaque TTC36 (99% identical), chimpanzee TTC36 (98% identical), dog TTC36 (89% identical), mouse Ttc36 (89% identical), rat Ttc36 (88% identical), guinea pig TTC36 (87% identical), rabbit TTC36 (86% identical), tropical clawed frog ttc36 (61% identical), zebrafish ttc36 (59% identical), Caenorhabditis elegans ttc-36 (43% identical), Drosophila melanogaster CG14105 (39% identical).
Diseases named in the same sentence as TTC36 in open-access papers:
TTC36 is named in the same sentence as 12 diseases in open-access papers, as found by Europe PMC text mining. Sharing a sentence is not in itself a finding about the gene and the disease. The quoted sentences say what the papers report.
hepatocellular carcinoma (5 papers, 2019 to 2025). A malignant tumor that arises from hepatocytes. "It is interesting to note that TTC36 (also called HBP21) encodes a poorly characterized tumor suppressor whose loss of function has been associated with hepatocellular carcinoma." (PMID 30548174, 2019). "This study establishes TTC36 as a pivotal tumor suppressor in hepatocellular carcinoma that orchestrates a previously unrecognized TTC36/YBX3/SPRED1 signaling axis which suppresses Ras/MAPK pathway to constrain tumor proliferation." (PMID 41208883, 2025). "TTC36 was reported to be a tumor suppressor in gastric cancer and hepatocellular carcinoma though the Wnt-β-catenin signaling pathway and promotion of cell apoptosis." (PMID 35751103, 2022). "In hepatocellular carcinoma (HCC), silencing of tumor suppressor genes such as HHIP, MT1M, PZP, and TTC36 is a key driver of carcinogenesis." (PMID 41335282, 2025).
breast carcinoma (3 papers, 2017 to 2022). "Contrary to the results of this study, a previous study revealed that TTC36 was highly expressed in breast cancer tissue." (PMID 35751103, 2022). "In the tissue group including breast–mammary and the two adipose tissues, the top tissue-specific TE-IR hub was TTC36, a gene highly expressed in breast cancer." (PMID 29021288, 2017).
gastric cancer (3 papers, 2021 to 2022). A primary or metastatic malignant neoplasm involving the stomach. "This study aimed to investigate the role of TTC36 in human gastric carcinoma (GC) and explore the potential underlying mechanisms." (PMID 33854620, 2021). "And effects of TTC36 expression on the prognosis of patients with gastric carcinoma were analyzed using the data from the GEO database." (PMID 33854620, 2021). "In summary, this research revealed that TTC36 is a putative tumor suppresser in gastric cancer." (PMID 33854620, 2021). "In order to investigate whether TTC36 expression is different between normal stomach epithelial cell and GC cells, the mRNA and protein levels of TTC36 were measured in stomach epithelial cell line GES-1 and four gastric carcinoma cell lines, including AGS, BGC823, MGC-803 and MKN45, respectively." (PMID 33854620, 2021).
liver cancer (3 papers, 2021 to 2023). An epithelial or non-epithelial malignant neoplasm that arises from the liver. "Although there are no relevant reports on obesity or adipose tissue for TTC36, few studies have found that TTC36 was negatively regulated by TTC36 methylation in liver cancer tissues, and it is involved in the process of immune infiltration." (PMID 36313453, 2022). "Among these genes, TTC36 was discovered as a new liver cancer prognostic marker after reviewing the newest literature in the PubMed database." (PMID 34646759, 2021). "These analyses demonstrated that HHIP was a key TSG controlling liver cancer cell proliferation and cell viability; in fact, only modest changes in cell viability were achieved when individually targeting MT1M, PZP, and TTC36." (PMID 37120619, 2023).
Obesity (3 papers, 2022 to 2025). Accumulation of substantial excess body fat. "In another integrative methylome–transcriptome analysis, seven key genes were identified—CCRL2, GPT, LGALS12, PC, SLC27A2, SLC4A4, and TTC36—that were hypermethylated in obesity and concurrently showed reduced expression." (PMID 41303351, 2025). "RGS12, which was differentially expressed in visceral adipose tissue from morbidly obese patients, and TTC36, which is involved in the occurrence and development of obesity, likely through the immune microenvironment, have both garnered recent attention." (PMID 38550599, 2024). "In summary, we successfully identified seven key genes, namely, CCRL2, GPT, LGALS12, PC, SLC27A2, SLC4A4, and TTC36, which are involved in obesity occurrence and development likely through the immune microenvironment." (PMID 36313453, 2022). "In this study, by analyzing three GEO datasets and verifying in 24 patients, we identified that CCRL2, GPT, LGALS12, PC, SLC27A2, SLC4A4, and TTC36 might be the key genes that play an important role in obesity pathogenesis." (PMID 36313453, 2022).
tyrosinemia (3 papers, 2019 to 2025). An autosomal recessive inherited metabolic disorder caused by mutations in the FAH, HPD, and TAT genes. "TTC36, previously identified in our murine model, was found to be closely associated with tyrosinemia." (PMID 40274799, 2025). "Knockout of Ttc36 in mice reduces HPD expression in liver and leads to tyrosinemia phenotypes with neuropathological changes and impaired learning and memory." (PMID 31537781, 2019).
prostate tumors (1 paper, 2019). "In addition, our work indicated the presence of additional novel fusion partners such as TTC36 in prostate tumors, located in the same 11q23.3 locus and separated by < 640 bp in a normal chromosome 11q23.3 locus." (PMID 30548174, 2019).
tumor (10 papers, 2019 to 2025). "Histologically, TTC36-knockout mice displayed smaller tumor necrotic areas, fewer proliferating cells (as indicated by reduced Ki-67 immunoreactivity), and impaired tumor growth." (PMID 40274799, 2025). "In summary, our findings demonstrate that TTC36 functions as a tumor suppressor in HCC by inhibiting the Ras/MAPK signaling pathway via YBX3/SPRED1 axis." (PMID 41208883, 2025). "In subcutaneous xenografts, TTC36 overexpression significantly reduced tumor volume/weight and Ki-67 levels, while knockdown increased both versus control group after 28 days." (PMID 41208883, 2025). "Collectively, TTC36 emerges as a ​predominantly hepatocyte-expressed putative tumor suppressor​ in HCC, where its downregulation is consistently associated with poor clinical outcomes." (PMID 41208883, 2025). "The TTC36/YBX3/SPRED1 axis inhibits tumor growth but induces sorafenib resistance via compensatory PI3K/Akt activation." (PMID 41208883, 2025). "In vivo, subcutaneous xenografts recapitulated the TTC36-SPRED1 regulatory axis: ​TTC36 overexpression significantly inhibited tumor growth." (PMID 41208883, 2025). "Next, the expression level of TTC36 was further verified via qRT-PCR in an expanded cohort of 80 paired HCC tumor and para-tumor tissues." (PMID 41208883, 2025). "Although our results suggest that TTC36 promotes tumor proliferation in a c-Myc-dependent manner, direct evidence linking TTC36 silencing to activation of the Wnt/β-catenin pathway is lacking in this study." (PMID 40274799, 2025). "Here, we elucidate a novel TTC36-centered tumor-suppressive axis in HCC to directly addressing these critical knowledge gaps." (PMID 41208883, 2025). "Collectively, these results demonstrate that TTC36 downregulation promotes tumor proliferation both in vitro and in vivo." (PMID 41208883, 2025). "In particular, the high methylation levels of 2 CpGs (cg24222440 and cg16806210) of TTC36 both had a positive correlation trend with the pathologic tumor staging of HCC via SurvivalMeth automated analysis." (PMID 36421714, 2022). "The overexpression of TTC36 notably inhibited tumor progression, cell cycle G1/S transfer and increased apoptosis in AGS cells." (PMID 33854620, 2021). "Taken together, these findings indicated a tumor-suppressive role of TTC36 in GC, and suggest the clinical significance of TTC36 in GC prognosis." (PMID 33854620, 2021). "Genes whose growth profiles most similarly match the T cell growth when stimulated by IL-2 include genes such as: TMEM74B and TTC36, a transmembrane protein and a tumor suppressor." (PMID 33105566, 2020). "After systematically screening the functional annotations and existed literature reports of 309 down-regulated differentially expressed genes, TTC36 captured our attention as a ​poorly characterized putative tumor suppressor​ for HCC that ​warrants in-depth mechanistic investigation." (PMID 41208883, 2025). "This is the first study reporting the antioncogenic roles of TTC36 in tumor." (PMID 35846428, 2022). "Typical ones as β-defensin-1 (DEFB1), growth arrest and DNA damage-inducible gamma (GADD45G), HSP70 binding protein 21 (encoded by TTC36) that protect the organism from and down-regulated in HCC or multiple tumor types, were significantly decreased in liver of TG vs. WT pigs." (PMID 34322121, 2021). "The combination of TTC36 and Hsp70 may contribute to rescue tumor cells from programmed cell death." (PMID 33854620, 2021). "The result revealed that TTC36 is predominantly expressed in hepatocytes (both normal hepatocytes in adjacent tissues and HCC cells in tumor tissues), with negligible expression in other cell types." (PMID 41208883, 2025). "In animal models, the tumor growth analysis, along with IHC staining and TUNNEL staining, was used to investigate the function of TTC36 and the response to sorafenib." (PMID 41208883, 2025).
tumor (continued). "In summary, the findings indicate that TTC36, which is highly expressed in HCC, exerts a tumor-promoting function in HCC by facilitating cell proliferation, advancing cell cycle progression, and enhancing migration, rather than triggering apoptosis." (PMID 40274799, 2025). "Building on our findings that TTC36 constrains HCC proliferation via suppressing Ras/MAPK signaling, we hypothesized that high TTC36 level may force tumor cells to rely on alternative proliferation-promoting pathways, thereby inducing resistance to sorafenib." (PMID 41208883, 2025). "Low TTC36 expression correlated with reduced infiltration of B cells, CD4+ T cells, dendritic cells, and neutrophils, suggesting TTC36 may function as a potential regulator of the tumor immune microenvironment." (PMID 41208883, 2025). "So far, the function of TTC36 in human tumor has not been studied extensively." (PMID 33854620, 2021).
cancer (3 papers, 2021 to 2025). A tumor composed of atypical neoplastic, often pleomorphic cells that invade other tissues. "The correlations between TTC36 and cancer immune infiltrates were investigated via TIMER." (PMID 35846428, 2022).
TTC36 also shares sentences with these, for which no sentence is quoted: clear cell renal cell carcinoma (1 paper); idiopathic interstitial pneumonia (1); proliferative vitreoretinopathy (1).